ATP6AP2 (ATPase H+ transporting accessory protein 2)
Description:
Multifunctional protein which functions as a renin, prorenin cellular receptor and is involved in the assembly of the lysosomal proton-transporting V-type ATPase (V-ATPase) and the acidification of the endo-lysosomal system. May mediate renin-dependent cellular responses by activating ERK1 and ERK2. By increasing the catalytic efficiency of renin in AGT/angiotensinogen conversion to angiotensin I, may also play a role in the renin-angiotensin system (RAS). Through its function in V-type ATPase (v-ATPase) assembly and acidification of the lysosome it regulates protein degradation and may control different signaling pathways important for proper brain development, synapse morphology and synaptic transmission (By similarity).
Synonyms: ATP6M8-9; ATP6IP2; ELDF10; HT028; MSTP009; PRR; M8-9; RENR; (P)RR; APT6M8-9; CDG2R; MRXE; MRXSH; XMRE; XPDS
Tractability: Small molecule: a structure with a bound ligand is known; it has a high-quality binding pocket. Antibody: its Gene Ontology location is reachable by antibodies, with high confidence; UniProt places it where antibodies can reach, with medium confidence; UniProt predicts a signal peptide or a membrane-spanning region. PROTAC: ubiquitination databases record sites on it; its protein half-life has been measured.
Gene: Protein-coding gene on chromosome X (40,579,372 to 40,606,848, forward strand). Ensembl gene ENSG00000182220.
Subcellular location: Endoplasmic reticulum membrane; Lysosome membrane; Cytoplasmic vesicle, autophagosome membrane; Cell projection, dendritic spine membrane; Cell projection, axon; Endosome membrane; Cytoplasmic vesicle, clathrin-coated vesicle membrane; Cytoplasmic vesicle, secretory vesicle, synaptic vesicle membrane
Pathways (Reactome):
Developmental Biology: Regulation of MITF-M-dependent genes involved in lysosome biogenesis and autophagy
Immune System: Neutrophil degranulation
Metabolism of proteins: Metabolism of Angiotensinogen to Angiotensins
Gene Ontology:
Molecular function: protein binding; signaling receptor activity
Biological process: angiotensin maturation; central nervous system maturation; eye pigmentation; head morphogenesis; lysosomal lumen acidification; positive regulation of canonical Wnt signaling pathway; positive regulation of transforming growth factor beta1 production; positive regulation of Wnt signaling pathway; regulation of MAPK cascade; rostrocaudal neural tube patterning; endosomal lumen acidification; Golgi lumen acidification; intracellular pH reduction; proton transmembrane transport; vacuolar acidification; synaptic vesicle lumen acidification
Cellular component: endoplasmic reticulum membrane; external side of plasma membrane; extracellular exosome; lysosomal membrane; lysosome; membrane; vacuolar proton-transporting V-type ATPase complex; endosome membrane; ficolin-1-rich granule membrane; Golgi membrane; plasma membrane; proton-transporting V-type ATPase complex; tertiary granule membrane; vacuolar proton-transporting V-type ATPase, V0 domain; autophagosome membrane; axon; bounding membrane of organelle; clathrin-coated vesicle membrane; cytoplasm; dendritic spine membrane; synaptic vesicle membrane
Gene-disease validity (ClinGen):
ClinGen rates the evidence that ATP6AP2 causes each of these diseases.
ATP6AP2-related disorder (X-linked): Definitive. Variants in the gene ATP6AP2 have been associated with a multitude of diseases, including X-linked syndromic ID Hedera type, X-linked Parkinsonism-spasticity syndrome, and congenital disorder of glycosylation type 2R.
Homologues: Orthologues: chimpanzee ATP6AP2 (99% identical), macaque ATP6AP2 (99% identical), pig ATP6AP2 (95% identical), dog ATP6AP2 (94% identical), mouse Atp6ap2 (94% identical), rabbit ATP6AP2 (93% identical), guinea pig ATP6AP2 (93% identical), rat Atp6ap2 (92% identical), tropical clawed frog atp6ap2 (71% identical), zebrafish atp6ap2 (68% identical), Drosophila melanogaster ATP6AP2 (25% identical), Caenorhabditis elegans vha-20 (20% identical), and 1 more.
Diseases named in the same sentence as ATP6AP2 in open-access papers:
ATP6AP2 is named in the same sentence as 128 diseases in open-access papers, as found by Europe PMC text mining. Sharing a sentence is not in itself a finding about the gene and the disease. The quoted sentences say what the papers report.
Parkinsonism (11 papers, 2014 to 2024). Characteristic neurologic anomaly resulting from degeneration of dopamine-generating cells in the substantia nigra, a region of the midbrain, characterized clinically by shaking, rigidity, slowness of movement and difficulty with walking and gait. "ATP6AP2 mutations are found in X-linked ID with Parkinsonism and spasticity, and PRPS1 mutations in Arts syndrome, X-linked recessive Charcot-Marie-Tooth disease 5 and X-linked non-syndromic hearing loss." (PMID 36551904, 2022). "Recently, a meta-analysis of genome-wide association showed an inverse association between ATP6AP2 and multiple sclerosis, Alzheimer’s disease and Parkinson’s disease." (PMID 29751779, 2018). "Mutations of the ATPase H+ Transporting Accessory Protein 2 (ATP6AP2) gene cause a rare X-linked form of parkinsonism with spasticity." (PMID 29312935, 2017). "On the other hand the decreased expression of ATPase and ubiquitin genes (ATP6AP2, UBE2e1, and Ube2q1) prevent mitochondrial oxidative stress leading to Parkinson's disease, Alzheimer's and X-linked mental retardation." (PMID 28423529, 2017). "The dysregulation of ATP6AP2 was also reported to be implicated in Parkinsonism." (PMID 39342078, 2024). "Mutations in their encoding genes can lead to neurodegenerative disorders, such as Parkinson’s disease (ATP6AP2) and Ohtahara syndrome (DMXL2)." (PMID 39273013, 2024). "More recently additional quality control genes/mutations have been reported linked for Parkinsonism, including DNAJC6, DNAJC13, VPS35 and ATP6AP2." (PMID 25170892, 2014). "Two examples relevant to parkinsonism include 5′ UTR expansions in FMR1 in Fragile X-associated tremor-ataxia syndrome and non-coding mutations in ATP6AP2 that contribute to aberrant alternative splicing." (PMID 25061481, 2014). "A very rare form of parkinsonism (X-linked parkinsonism with spasticity, XPDS) shows pathological 4R TAU deposits and is caused by altered splicing of the ATPase H(+) transporting lysosomal accessory protein 2 (ATP6AP2) gene, which causes lysosomal dysfunction in XPDS." (PMID 38554150, 2024). "WES has become the fastest method for the identification of novel genes in parkinsonism, contributing to the discoveries of FBXO7, WRD45, DNAJC6, DNAJC13, ATP6AP2 and SYNJ1 in recent years." (PMID 25061481, 2014).
diabetes (10 papers, 2010 to 2024). "ATP6AP2 deficiency is the exacerbated generation and accumulation of multigranular bodies that consume the cytoplasm of beta cells, ensnaring insulin secretory granules (SGs) and thus causing insulin-deficient diabetes." (PMID 35885938, 2022). "We find that ATP6AP2 is critical for the regulation of insulin and is key to the maintenance of beta cell function and the prevention of diabetes." (PMID 35885938, 2022). "In addition, ATP6AP2 is critical for regulating the stored insulin pool and a balanced regulation of granule turnover is key to maintaining beta cell function and diabetes prevention." (PMID 35885938, 2022). "Additionally, the elevated prorenin/renin levels characteristic of diabetes may contribute to the activation of renal ATP6AP2 and subsequent development of diabetic nephropathy." (PMID 33326313, 2021).
diabetic cardiomyopathy (8 papers, 2019 to 2024). Diabetic cardiomyopathy is a disorder of the heart muscle in people with diabetes. "Our previous research showed that ATP6AP2/PRR has high expression and participation in fibrosis in diabetic cardiomyopathy and alcoholic cardiomyopathy." (PMID 35379787, 2022).
Cognitive impairment (6 papers, 2018 to 2023). Abnormal cognition is characterized by deficits in thinking, reasoning, or remembering. "For example, altered splicing and conditional knockout of the ATP6AP2 gene in mouse and fly have been shown to cause cognitive impairment and other congenital disorders associated with neurodegeneration." (PMID 32393395, 2020). "Conditional knockdown or deletion of ATP6AP2 (encodes for ATP6AP2, an essential accessory component of V-ATPase), leads to the appearance of autophagic vacuoles, and subsequent neurodegeneration and cognitive impairment in both Drosophila and mouse models." (PMID 37287072, 2023). "Patients with exon-skipping mutations in ATP6AP2 show cognitive disorders such as XPDS." (PMID 32393395, 2020). "Human ATP6AP2/PRR is known to be a Parkinsonism candidate gene and its mutations in humans, mice or flies can lead to cognitive impairment, neurodegeneration and epilepsy." (PMID 34620624, 2021). "In the mouse and fly, conditional depletion of ATP6AP2 induces cognitive impairment and neurodegeneration, and regulation of adult hippocampal neurogenesis via Wnt/PCP/β-catenin pathways." (PMID 29751779, 2018). "Lack of Atp6ap2 leads to cognitive impairment and neurodegeneration, and mutations of Atp6ap2 in humans are associated with intellectual disability." (PMID 34417446, 2021).
colorectal cancer (6 papers, 2019 to 2023). A primary or metastatic malignant neoplasm that affects the colon or rectum. "Recent studies linked ATP6AP2 up-regulation to the progression of glioma and colorectal cancer, due to its roles in aberrant activation of the Wnt/beta-catenin signalling pathway." (PMID 33237942, 2020).
diabetic nephropathy (5 papers, 2008 to 2024). "Since beta cells are the key cells leading to T2D, we search for hub genes in CCSN of beta cells and find that ATP6AP2 is essential for regulation and storage of insulin, and the renin-angiotensin system involving ATP6AP2 is related to most pathological processes leading to diabetic nephropathy." (PMID 35885938, 2022). "Supporting this hypothesis, treatment of type 1 and type 2 diabetic rats or mice with a peptide inhibitor of ATP6AP2 significantly inhibited the development of diabetic nephropathy." (PMID 33326313, 2021).
endometrial cancer (5 papers, 2020 to 2024). Primary or metastatic malignant neoplasm involving the endometrium (mucous membrane that lines the endometrial cavity). "A study of 30 endometrial cancer samples showed that high expression of ATP6AP2, AGTR1, and ACE1 in the RAS was associated with the spread of endometrial cancer." (PMID 39257906, 2024). "ATP6AP2 was also shown to be a key component of the pro-angiogenic/proliferative arm of the RAS, which plays a role in the growth and spread of endometrial cancer." (PMID 33237942, 2020). "The increased expression of AGTR1, ATP6AP2, and ACE1, crucial components of the RAS’s pro-angiogenic/proliferative arm, raises the possibility that the RAS is involved in the development and progression of endometrial cancer." (PMID 37869088, 2023).
glioma (5 papers, 2020 to 2024). A benign or malignant brain and spinal cord tumor that arises from glial cells (astrocytes, oligodendrocytes, ependymal cells). "Targeting renin using synthetic renin inhibitors induced apoptosis and reduced the growth of commercial glioma cells in vitro, while a similar observation was reported using an siRNA against ATP6AP2." (PMID 38607073, 2024). "A monoclonal antibody against ATP6AP2 was also shown to reduce glioma sphere growth, induce apoptosis and reduce tumour growth in a subcutaneous xenograft glioma model." (PMID 38607073, 2024).
heart failure (5 papers, 2020 to 2023). Inability of the heart to pump blood at an adequate rate to meet tissue metabolic requirements. "In cardiomyocytes, ATP6AP2 is essential for vacuolar H+-ATPase assembly, and the loss-of-function could result in lethal heart failure." (PMID 38075676, 2023). "To further confirm the effect of ATP6AP2 upregulation in heart failure, we generated ATP6AP2 gain-of-function transgenic mice." (PMID 35379787, 2022). "When ATP6AP2 knockout was specifically performed in cardiomyocytes or podocytes, mice developed lethal heart failure, nephrotic syndrome, and albuminuria." (PMID 35379787, 2022). "(iii) NLRP3 inflammasome significantly increases in TAC-induced heart failure after ATP6AP2 knockdown." (PMID 35379787, 2022). "We have proved that ATP6AP2 knockdown increased NLRP3 expression in TAC-induced heart failure." (PMID 35379787, 2022). "(i) Knockdown of ATP6AP2 deteriorates heart function in TAC-induced heart failure." (PMID 35379787, 2022). "NLRP3 inhibition has a definite protective effect in ATP6AP2 knockdown-induced heart failure." (PMID 35379787, 2022). "Our results show ATP6AP2 upregulation can be seen from the hypertrophic phase until heart failure." (PMID 35379787, 2022). "Adenovirus-mediated knockdown of ATP6AP2(shR-ATP6AP2) accelerated the progress of heart failure." (PMID 35379787, 2022). "In the present study, we investigate the regulative relation of ATP6AP2, autophagic flux, and NLRP3 inflammasome activation in the progression of cardiac hypertrophy and heart failure." (PMID 35379787, 2022).
Obesity (5 papers, 2018 to 2024). Accumulation of substantial excess body fat. "This raises important future questions, not only regarding the function of ATP6AP2 in renal lipid transport, but also its role in proximal tubule lipid accumulation in the setting of obesity related kidney injury." (PMID 39134597, 2024). "Further investigation should determine whether ATP6AP2 contributes to obesity related ectopic lipid deposition in the proximal tubule." (PMID 39134597, 2024).
breast carcinoma (3 papers, 2020 to 2023). "A decline in ATP6AP2 triggers aberrant pH levels that impair lysosomal function and cause immune profile changes in senescent breast cancer cells." (PMID 37993606, 2023). "To further explore the association between ATP6AP2 and cellular senescence, we validated the senescence-related phenotypes in breast cancer cells." (PMID 37993606, 2023). "Among these subunits, we demonstrated that ATP6AP2 was downregulated in therapy-induced senescent breast cancer cells, causing intracellular acidification (reduction in pHi) and lysosomal alkalinization (elevation in pHL)." (PMID 37993606, 2023). "To gain comprehensive insights into the regulatory role of ATP6AP2 in cellular pH homeostasis and its impact on the senescence process in breast cancer cells, we conducted an experimental design employing ATP6AP2 knockdown depicted in a schematic diagram." (PMID 37993606, 2023). "Herein, we report the regulatory role of ATP6AP2 in senescent breast cancer cells treated with doxorubicin (Doxo) and abemaciclib (Abe)." (PMID 37993606, 2023). "In conclusion, our findings demonstrated that attenuated ATP6AP2 expression triggered intracellular acidification (pHi decrease) and lysosomal alkalinization (pHL increase) in senescent breast cancer cells exposed to Doxo and Abe." (PMID 37993606, 2023). "The results demonstrated a substantial suppression of ATP6AP2 expression in knockdown breast cancer cells." (PMID 37993606, 2023). "However, the function of ATP6AP2 in regulating pHi homeostasis in doxorubicin (Doxo) and abemaciclib (Abe)-challenged breast cancer is unclear." (PMID 37993606, 2023). "Moreover, the knockdown of ATP6AP2 induced cellular senescence in breast cancer cells, accompanied by changes in SASP expression." (PMID 37993606, 2023). "ATP6AP2–a hub gene–is correlated with breast cancer immune infiltration and lysosomal function." (PMID 37993606, 2023).
COVID-19 (3 papers, 2021 to 2025). A disease caused by infection with severe acute respiratory syndrome coronavirus 2. "Thus, local expression of ATP6AP2 may be a key enzyme for neurodegenerative diseases linking intracellular trafficking with disease progression, i.e., post-COVID-19." (PMID 38674105, 2024).
cutis laxa (3 papers, 2020 to 2024). Cutis laxa (CL) is an inherited or acquired connective tissue disorder characterized by wrinkled, redundant and sagging inelastic skin associated with skeletal and developmental anomalies and, in some cases, with severe systemic involvement. "Genetic reduction of ATP6AP2 for example by hemizygous missense mutations in the extracellular domain of the accessory V-ATPase subunit of ATP6AP2 has been described to lead to a glycosylation disorder with liver disease, immunodeficiency, cutis laxa, and psychomotor impairment." (PMID 38674105, 2024). "In this study, we identified the first Chinese patient diagnosed with ATP6AP2-CDG, presenting with recurrent jaundice, cutis laxa, cirrhosis, growth retardation, coagulopathy, anemia, and cardiomegaly." (PMID 38075676, 2023).
diabetic retinopathy (3 papers, 2013 to 2022). "Prorenin, the natural ligand for ATP6AP2, is elevated in the plasma of patients with microvascular complications related to diabetic retinopathy." (PMID 35998033, 2022). "Blocking ATP6AP2 activity prevented cardiac fibrosis and diabetic retinopathy in hypertensive and diabetic rats, respectively." (PMID 35998033, 2022).
granular cell tumor (3 papers, 2018 to 2022). An unusual benign or malignant neoplasm characterized by the presence of neoplastic large polygonal cells with granular, eosinophilic cytoplasm which contains abundant lysosomes. "Silencing of ATP6AP1 and ATP6AP2 in vitro resulted in vesicle acidification impairment, endosomal compartmental redistribution and intracytoplasmic granule accumulation that closely mimicked the granular cell tumor phenotype." (PMID 32365590, 2020).
Immunodeficiency (3 papers, 2020 to 2024). Failure of the immune system to protect the body adequately from infection, due to the absence or insufficiency of some component process or substance. "In humans, ATP6AP2 mutations have been linked to steatohepatitis, immunodeficiency, and neurodegenerative diseases." (PMID 38674105, 2024).
liver disease (3 papers, 2020 to 2024). "Since ATP6AP2-CDG causes liver disease mainly, autophagy flux was explored in those patients." (PMID 38075676, 2023).
lung carcinoma (3 papers, 2020 to 2023). "As such, ATP6AP2 expression is involved in lung cancer cell proliferation and progression through the regulation of autophagy." (PMID 37588662, 2023). "For example, miR‐140‐3p could limit lung cancer cell viability and metastasis via decreasing ATP6AP2 expression." (PMID 33244865, 2021).
X-linked parkinsonism with spasticity (3 papers, 2017 to 2024). "Such a link is evident in X-linked parkinsonism with spasticity (XPDS), which is associated with a mutation in ATP6AP2, which causes altered splicing of this prorenin receptor, a key regulator of V-ATPase function." (PMID 28468938, 2017).
Breast Invasive Carcinoma (2 papers, 2020 to 2023). "We identified a significant upregulation in ATP6AP2 expression among the tumor groups by analyzing The Cancer Genome Atlas Breast Invasive Carcinoma (TCGA-BRCA) data." (PMID 37993606, 2023).
colon cancer (2 papers, 2020 to 2023). "However, there is little association between the transcriptional levels of ATP6AP2 and Wnt3 in colon cancer (r = 0.25)." (PMID 36597142, 2023).